ALAD (aminolevulinate dehydratase)
Description:
Catalyzes an early step in the biosynthesis of tetrapyrroles. Binds two molecules of 5-aminolevulinate per subunit, each at a distinct site, and catalyzes their condensation to form porphobilinogen.
Synonyms: ALADH; PBGS
Tractability: Small molecule: a structure with a bound ligand is known. Antibody: its Gene Ontology location is reachable by antibodies, with high confidence. PROTAC: ubiquitination databases record sites on it; its protein half-life has been measured.
Target class: Enzyme; Lyase
Gene: Protein-coding gene on chromosome 9 (113,386,304 to 113,401,356, reverse strand). Ensembl gene ENSG00000148218.
Subcellular location: Cytoplasm, cytosol
Subcellular location (Human Protein Atlas): Cytosol
Pathways (Reactome):
Immune System: Neutrophil degranulation
Metabolism: Heme biosynthesis
Gene Ontology:
Molecular function: identical protein binding; lead ion binding; porphobilinogen synthase activity; zinc ion binding; catalytic activity; metal ion binding; proteasome core complex binding
Biological process: heme B biosynthetic process; heme biosynthetic process; negative regulation of proteasomal protein catabolic process; protein homooligomerization; cellular response to lead ion; heme A biosynthetic process; response to activity; response to aluminum ion; response to amino acid; response to arsenic-containing substance; response to cadmium ion; response to cobalt ion; response to ethanol; response to fatty acid; response to glucocorticoid; response to herbicide; response to hormone; response to hypoxia; response to ionizing radiation; response to iron ion; response to lead ion; response to lipopolysaccharide; response to mercury ion; response to metal ion; response to methylmercury; and 12 more
Cellular component: extracellular exosome; nucleus; cytosol; extracellular region; ficolin-1-rich granule lumen; secretory granule lumen
Genetic constraint (gnomAD): Loss-of-function variants: 20 observed, 46.1 expected, observed/expected ratio (o/e) 0.43, 90% interval 0.3 to 0.63. The upper end of that interval is the gene's LOEUF score, 0.63, which puts it in group 2 of 6, group 1 being the genes least tolerant of losing a copy. Missense variants: 323 observed, 466.46 expected, observed/expected ratio (o/e) 0.69, 90% interval 0.63 to 0.76. Synonymous variants: 156 observed, 177.06 expected, observed/expected ratio (o/e) 0.88, 90% interval 0.77 to 1.01.
Gene-disease validity (ClinGen):
ClinGen rates the evidence that ALAD causes each of these diseases.
porphyria due to ALA dehydratase deficiency (autosomal recessive): Moderate. A hepatic porphyria caused by biallelic variants in ALAD (in an autosomal recessive inheritance pattern).
Homologues: Orthologues: chimpanzee ALAD (99% identical), dog ALAD (95% identical), guinea pig ALAD (95% identical), rabbit ALAD (94% identical), pig ALAD (92% identical), mouse Alad (89% identical), macaque ALAD (88% identical), rat Alad (88% identical), tropical clawed frog alad (78% identical), zebrafish alad (74% identical), Drosophila melanogaster Pbgs (60% identical).
Diseases named in the same sentence as ALAD in open-access papers:
ALAD is named in the same sentence as 53 diseases in open-access papers, as found by Europe PMC text mining. Sharing a sentence is not in itself a finding about the gene and the disease. The quoted sentences say what the papers report.
anemia (13 papers, 2010 to 2025). A reduction in the number of red blood cells, the amount of hemoglobin, and/or the volume of packed red blood cells. "It is not surprising that mutations in proteins responsible for ISC transfer can cause anemia because two of the eight enzymes catalyzing heme biosynthesis, namely aminolevulinate dehydratase and ferrochelatase, were identified to be iron–sulfur proteins." (PMID 38757931, 2024). "The determination of ALAD activity is well suited as a measure of lead-induced anemia to differentiate iron deficiency or inhibition of hemoglobin synthesis." (PMID 32784669, 2020). "Previous studies reported Pb-induced anemia caused by the inhibitory effect of Pb on δ-aminolevulinic acid dehydratase (ALAD), which plays a significant role in heme synthesis, in addition to the formation of basophilic stippling in red blood cells with short life spans." (PMID 31877779, 2019). "One of the main reasons for lead poisoning causing anaemia is that lead interferes with the activity of an essential enzyme called delta-aminolevulinic acid dehydratase, or ALAD, which is important in the biosynthesis of heme, the cofactor found in haemoglobin." (PMID 27486361, 2015). "An ALAD activity assay could and should be a diagnostic bioassay to evaluate both acute and chronic anemia induced by occupational and environmental exposure to lead and differentiate it from common causes of anemia, such as malnutrition or heredity." (PMID 32784669, 2020). "For example, Pb-induced anemia occurs via the inhibition of two enzymes of heme biosynthesis: ALAD and ferrochelatase." (PMID 33927623, 2021). "Farant and Wigfield reported that inhibition of ALAD, a cytosolic sulfydryl enzyme and ferrochelatase by lead resulted in depressed heme synthesis that ultimately led to anemia." (PMID 21042466, 2010). "Anemia may develop with Pb poisoning via the inhibition of ferrochelatase and δ-aminolevulinic acid dehydratase (ALAD), the two of many enzymes involved in heme biosynthesis." (PMID 33927623, 2021). "The inhibition of ferrochelatase and ALAD by lead decreases heme synthesis which leads to anemia." (PMID 33927623, 2021).
Acute porphyrias (4 papers, 2012 to 2021). "This is the case of the homozygous patients with ALAD deficiency, lead poisoning and hereditary tyrosinemia deficiency where the hepatic ALAD activity is less than 1% of the reported normal activity." (PMID 22412963, 2012). "In fact, the inhibition of ALAD is only significant for ALA accumulation when important ALAD deficiency is observed." (PMID 22412963, 2012).
hemochromatosis (4 papers, 2004 to 2025). A disorder of iron metabolism characterized by a triad of HEMOSIDEROSIS; LIVER CIRRHOSIS; and DIABETES MELLITUS. "We evaluated associations of manganese with functional variants in three candidate iron metabolism genes: HFE [hemochromatosis], TF [transferrin], and ALAD [δ-aminolevulinic acid dehydratase]." (PMID 22074419, 2011). "Although the specific genes remain to be fully characterized, polymorphisms in the vitamin D receptor (VDR), δ-aminolevulinic acid dehydratase (ALAD), and hemochromatosis (HFE) genes have all been implicated in differential lead absorption, retention, and excretion." (PMID 40457304, 2025). "Three genes are currently believed to play a role in lead neurotoxicity: the ALAD gene, which codes for δ-aminolevulinic acid dehydratase; the vitamin D receptor (VDR) gene; and the hemochromatosis gene coding for a defective protein known as HFE." (PMID 15198918, 2004).
breast carcinoma (3 papers, 2020 to 2023). "Another enzyme encoded by ALAD is overexpressed in breast cancer patients with a favorable clinical outcome." (PMID 33424926, 2020). "For instance, NDST1, FRZB, ALAD, EDNRB, SSX2IP, and SFN have strong associations with breast cancer development, which bolsters our confidence in the viability of our model." (PMID 38007443, 2023).
glioma (3 papers, 2005 to 2021). A benign or malignant brain and spinal cord tumor that arises from glial cells (astrocytes, oligodendrocytes, ependymal cells). "ALAD genotype was determined for 94% of these samples (355 glioma, 151 meningioma, 67 acoustic neuroma, and 505 controls)." (PMID 16140629, 2005). "In this sense, we recently observed significant differences in the mRNA expression in 8 of 11 analyzed genes (HMBS, UROD, FECH, PPOX, SLC15A2, ALAD, UROS, and ABCB6) involved in the heme biosynthesis between WHO grade II and IV gliomas." (PMID 33562253, 2021). "Significant differences in mRNA expression included increases of HMBS, UROD, FECH and PPOX as well as decreases of SLC15A2, ALAD, UROS and ABCB6 in WHO IV gliomas." (PMID 32722247, 2020).
hypochromic anemia (3 papers, 2018 to 2023). Anemia caused by the reduction of hemoglobin in relation to the red cell volume. "It inactivates δ-ALAD and ferrochelatase (thus inhibiting heme biosynthesis and causing hypochromic anemia), and reduces the activity of the most important antioxidant enzymes: superoxide dismutase (SOD), catalase (CAT), and glutathione peroxidase (GPX)." (PMID 37048229, 2023). "Lead has been shown to inhibit heme synthesis by altering the activities of δ-amino levulinic acid dehydratase [ALAD] thereby inducing microcytic and hypochromic anemia." (PMID 30619808, 2018).
Acute hepatic porphyria (2 papers, 2021 to 2023). Acute hepatic porphyrias represent a sub-group of porphyrias (see this term) characterized by the occurrence of neuro-visceral attacks with or without cutaneous manifestations. "Acute hepatic porphyria (OMIM#612740) is an inherited metabolic disorder caused by variants in the ALAD gene, that encodes the protein porphobilinogen synthase, a protein involved in hepatic heme synthesis." (PMID 32391605, 2021).
brain tumor (2 papers, 2005 to 2011). "Recent work on ALAD polymorphsims and risk of brain tumors suggests an increased risk for meningioma among participants with the ALAD G177C homozygous genotype." (PMID 21799727, 2011). "The enzyme δ -aminolevulinic acid dehydratase (ALAD), which catalyzes the second step of heme synthesis, can be inhibited by several chemicals, including lead, a potential risk factor for brain tumors, particularly meningioma." (PMID 16140629, 2005). "The specific question of ALAD genotype and brain tumor risk has not been addressed previously in the literature." (PMID 16140629, 2005).
Congenital erythropoietic porphyria (2 papers, 2014 to 2022). "The porphyrias are inherited by a dominant autosomal mechanism, except in the cases of congenital erythropoietic porphyria (CEP) and delta-aminolevulinic acid dehydratase (ALAD) deficiency, which are inherited by a recessive autosomal mechanism." (PMID 25145892, 2014).
diabetes (2 papers, 2012 to 2022). "In diabetes mellitus, impaired liver function is associated with decreased hepatic delta-aminolevulinic acid dehydratase (δ-ALAD) activity." (PMID 35883849, 2022).
liver cancer (2 papers, 2024 to 2025). An epithelial or non-epithelial malignant neoplasm that arises from the liver. "Among heme biosynthesis enzymes, only the first two-step genes ALAS1 and ALAD were downregulated in liver cancer lines." (PMID 39199347, 2024).
meningioma (2 papers, 2005 to 2011). A generally slow growing tumor attached to the dura mater. "In order to clarify the role of lead (or other chemicals) in the observed relationship between ALAD genotype and risk of meningioma, it will be important to conduct a detailed exposure assessment and evaluate the joint effect of exposure and ALAD genotype in this, or another, study population." (PMID 16140629, 2005). "However, the role of lead in the observed association between ALAD genotype and meningioma can be meaningfully addressed only when data on both ALAD genotype and individual lead exposure are available." (PMID 16140629, 2005). "The observation that the relationship between ALAD2 and risk of meningioma was stronger in men than in women could be due to biologic differences or differential exposure to a chemical agent modified by ALAD genotype." (PMID 16140629, 2005).
Zinc deficiency (2 papers, 2012 to 2023). A deficiency of the essential metal Zinc; an essential cofactor for many enzymes. "One outstanding candidate might be ALAD, also called porphobilinogen synthase (PBGS), an enzyme requiring zinc as a cofactor; in a state of severe zinc deficiency, ALAD could thus become the rate-limiting step, resulting in a lack of hemoglobin synthesis." (PMID 22563477, 2012).
amnesia (1 paper, 2012). Pathologic partial or complete loss of the ability to recall past experiences ( AMNESIA, RETROGRADE) or to form new memories ( AMNESIA, ANTEROGRADE). "The results showed that the incidences of debilitation, amnesia and dreaminess were much higher in the ALAD 1-1 genotype subgroup with more than 5 years on the job or lead exposure (P < 0.05)." (PMID 22851944, 2012).
cognitive deficit (1 paper, 2014). "Thus, this study was conducted to examine whether age-related cognitive deficit is associated with oxidative damage, especially with inhibition of the enzyme delta-aminolevulinate dehydratase (ALA-D), as well as to verify the influence of some metals in the enzyme activity and cognitive performance." (PMID 25329536, 2014).
Doss porphyria (1 paper, 2024). "Additionally, ALA (delta-aminolevulinic acid) dehydratase deficiency porphyria (also known as ALAD deficiency or Doss porphyria) is an autosomal recessive disease caused by biallelic variants on ALAD gene, which is responsible for the production of delta-aminolevulinate dehydratase enzyme." (PMID 38715693, 2024).
essential tremor (1 paper, 2015). A relatively common disorder characterized by a fairly specific pattern of tremors which are most prominent in the upper extremities and neck, inducing titubations of the head. "Case–control studies suggest an association between blood lead and essential tremor, and that this association is modified by polymorphisms in the δ-aminolevulinic acid dehydrogenase (ALAD) gene." (PMID 25633720, 2015).
genitourinary cancer (1 paper, 2018). "For instance, delta-aminolevulinic acid dehydratase (ALAD), a genitourinary cancer-related gene, is a target of lead." (PMID 30013948, 2018).
Hypertension (1 paper, 2010). The presence of chronic increased pressure in the systemic arterial system. "The main objective is to determine the role of the aminolevulinic acid dehydratase (ALAD) gene, which encodes the main carrier protein of lead in blood, in the association between lead exposure and blood pressure (BP) and hypertension in the U.S. population." (PMID 20123609, 2010).
insomnia (1 paper, 2012). A sleep disorder characterized by difficulty in falling asleep and/or remaining asleep. "According to the classification of self-conscious symptom frequency, the chi-square test was performed and the results showed that the incidences of vivid dreaminess and insomnia were higher in those with the ALAD 1-2 genotype than those with the ALAD 1-1 genotype (P < 0.05)." (PMID 22851944, 2012).
ischemia (1 paper, 2023). A hypoperfusion of the BLOOD through an organ or tissue caused by a PATHOLOGIC CONSTRICTION or obstruction of its BLOOD VESSELS, or an absence of BLOOD CIRCULATION. "Consistent with IR-associated changes in ALAD protein levels and enzymatic activities, the hepatic PBG level declined during ischemia and then partially recovered shortly after reperfusion." (PMID 37771779, 2023).
malaria (1 paper, 2015). Malaria is a serious and sometimes fatal disease caused by a parasite that commonly infects a certain type of mosquito which feeds on humans. "We note that prior work suggested a role for remnant host enzymes in heme biosynthesis by malaria parasites, but this prior proposal differed by positing that human enzymes such as ALAD were somehow imported and active within the parasite cytoplasm." (PMID 26173178, 2015).
ovarian carcinoma (1 paper, 2023). A malignant neoplasm originating from the surface ovarian epithelium. "The expression of ALAS2, HMBS, and FXN involved in iron utilization was associated with improved OS in ovarian cancer, whereas the expression of ALAD, ALAS1, and CPOX in this process was associated with poor OS in ovarian cancer." (PMID 38186569, 2023). "The expression of ALAS2 and HMBS involved in iron utilization was associated with improved PFS in ovarian cancer, whereas expression of ABCB7, ALAD, FXN, UROS, ISCU, and CPOX in this process was associated with poor PFS in ovarian cancer." (PMID 38186569, 2023).
renal carcinoma (1 paper, 2011). A carcinoma arising from the epithelium of the renal parenchyma or the renal pelvis. "The question of renal cancer risk associated with ALAD genotype has not been previously addressed in the literature." (PMID 21799727, 2011).
social phobia (1 paper, 2013). An anxiety disorder characterized by an intense, irrational fear of one or more social or performance situations in which the individual believes that he or she will be scrutinized by others. "This approach has enabled researchers to identify a SNP (rs817782) in the 3′ UTR of the aminolevulinate dehydratase gene (ALAD) that was shown to be associated with social phobia." (PMID 23150170, 2013).
tumor (4 papers, 2020 to 2025). "Additionally, enhanced activity of enzymes leading to the production of PpIX, such as aminolevulinate dehydratase (ALAD), uroporphyrinogen decarboxylase (UROD), and hydroxymethylbilane synthase (HMBS), has been observed in tumor cells." (PMID 35456936, 2022).
cancer (3 papers, 2011 to 2024). A tumor composed of atypical neoplastic, often pleomorphic cells that invade other tissues. "The ALAD genetic polymorphism (rs1800435) is associated with reduced cancer mortality." (PMID 38576019, 2024). "Furthermore, the G177C genetic polymorphism of ALAD alters lead toxicokinetics and adverse effects of lead exposure, and ALADCG/CC genotype is associated with reduced death rate from all causes and from cancer." (PMID 30013948, 2018). "In addition to finding that occupational lead exposure increased RCC risk, we observed some ALAD variants alone altered cancer risk, independent of lead exposure." (PMID 21799727, 2011).
infection (3 papers, 2019 to 2025). The state of being infected such as from the introduction of a foreign agent such as serum, vaccine, antigenic substance or organism. "The ALAD enzyme has only been produced during IC89 infection." (PMID 39992151, 2025). "However, the aminolevulinate dehydratase (ALAD) enzyme is only produced during IC89 infection." (PMID 39992151, 2025).
metabolic disorder (2 papers, 2021 to 2024). "AHP is an inherited metabolic disorder caused by variants in delta-aminolevulinic acid dehydratase (ALAD) gene." (PMID 38653753, 2024).
neurological disorders (1 paper, 2024). "Individuals carrying the variant allele ALAD rs1800435 G have a decrease in the activity of the enzyme, which can lead to an increase in Hg in the body and consequently to neurological disorders, such as changes in the visual field, memory deficits, distal neuropathy and amyotrophy of the toes." (PMID 38535959, 2024).
ALAD also shares sentences with these, for which no sentence is quoted: hereditary coproporphyria (7 papers); porphyria (4); variegate porphyria (4); acute intermittent porphyria (2); acoustic neuroma (1); active tuberculosis (1); autism (1); cognitive decline (1); endothelial dysfunction (1); erythropoietic porphyria (1); genetic diseases (1); hematological disorders (1); hepatoerythropoietic porphyria (1); Hodgkins lymphoma (1); latent infection (1); lung adenocarcinoma (1); microcytic anemia (1); multiple sclerosis (1); non-Hodgkin lymphoma (1); poisoning (1); porphyria cutanea tarda (1); renal cell carcinoma (1); respiratory diseases (1).